RNU6-715P (RNA, U6 small nuclear 715, pseudogene)
Gene: Small nuclear RNA gene on chromosome 2 (147,495,438 to 147,495,540, reverse strand). Ensembl gene ENSG00000202074.
Homologues: Orthologues: chimpanzee U6 (98% identical), rat U6 (81% identical), mouse Gm24207 (78% identical), guinea pig U6 (74% identical), mouse Gm24263 (73% identical). Paralogues in human: RNU6-1145P (89% identical), RNU6-38P (89% identical), RNU6-477P (89% identical), RNU6-393P (88% identical), RNU6-639P (88% identical), RNU6-1316P (87% identical), RNU6-183P (86% identical), RNU6-196P (86% identical), RNU6-20P (86% identical), RNU6-29P (86% identical), RNU6-73P (86% identical), RNU6-836P (86% identical), and 1287 more.